CTLA4 (cytotoxic T-lymphocyte associated protein 4)
Diseases named in the same sentence as CTLA4 in open-access papers (continued):
Sharing a sentence is not in itself a finding about the gene and the disease.
tumor (continued). "Several studies found that MDSCs and other molecules such as PD-L1 and CTLA-4 in tumor tissues are sensitive predictive markers for patients’ response to chemoradiotherapy for rectal cancer patients." (PMID 33384962, 2020). "To investigate on the role of CTLA-4 in tumor cells, we firstly tested the effects of ipilimumab on tumor cell growth when used in single treatment." (PMID 32024070, 2020). "Note that in reality, a minor population of tumour-infiltrating T cells continue to express CTLA4 alone or in combination with other checkpoints, but most of the published results agree that the main effect of CTLA4 takes place in the LNs." (PMID 33276543, 2020). "In the TILs, the PD-1 and CTLA-4 expression increased with tumor growth, and there were much higher levels when the tumor sizes were about 400 mm3 in each subpopulation (* P < 0.05)." (PMID 32805718, 2020). "By blocking these interactions, anti–PD-1, anti–CTLA-4 and anti–PD-L1 immunotherapies promote glycolytic metabolism in tumor-infiltrating T cells and improve their antitumor functions." (PMID 32375310, 2020). "Cytotoxic T lymphocyte-associated antigen 4 (CTLA4) and programmed death-1 (PD-1; encoded by the PDCD1 gene) represent crucial immune checkpoints, the blockade of which can potentiate anti-tumour immunity." (PMID 33225954, 2020). "Treatment with checkpoint inhibitors such as anti-PD-L1 or anti-CTLA-4 antibodies can block the immune checkpoint signaling pathways and boost the immune response against tumor cells in many types of cancer." (PMID 32752017, 2020). "Profiling of tumor infiltrates revealed that anti-CTLA4 blockade increased the percentage of both CD4+ and CD8+ T cells in wild-type mice over isotype." (PMID 32641748, 2020). "Consistent with published data, anti-CTLA4 or anti-PD1 alone significantly repressed tumor growth, which is comparable to that in KO group." (PMID 32477338, 2020). "Regression of primary MCF7 tumor and complete eradication of 4T1 lung metastasis were reported when combined with an anti‐CTLA‐4 antibody, providing a promising strategy for multimodal cancer treatment." (PMID 32328428, 2020). "Further work is required to elucidate the exactly different mechanism between A-498 and Caki-2 in PD-1/CTLA-4 pathway under the tumor microenvironment." (PMID 32349280, 2020). "ICIs, such as cytotoxic T lymphocyte antigen 4 (CTLA-4) and programmed death 1 (PD-1) suppress T cell-mediated anti-tumor immune responses, leading to tumor progression." (PMID 32050597, 2020). "Combining diclofenac treatment with single anti-PD-1 or dual checkpoint blockade (anti-PD-1 plus anti-CTLA-4) inhibited tumor growth and increased treatment response in two murine models, 4T1 TNBC and B16F10 melanoma." (PMID 33324565, 2020). "Immune checkpoint proteins, including PD-1 and cytotoxic T-lymphocyte-associated antigen 4 (CTLA-4), initiate signaling pathways that suppress T-cell anti-tumor effect." (PMID 33292551, 2020). "ICIs are monoclonal antibodies (mAbs) targeting checkpoint proteins expressed by immune cells or tumour cells, such as PD-1, programmed cell death protein-ligand 1 (PD-L1) and CTLA-4." (PMID 33574893, 2020). "CTLA-4 blockade promoted TIL growth from tumor fragments of 13 out of 14 (93%) patients compared to TIL growth from 9 out of 14 (64%) patients when tumor fragments were cultured in standard IL-2 conditions." (PMID 32127601, 2020). "Injection of anti-CTLA-4 antibody promotes anti-tumor immunity by enhancing the activation of T cells, thereby demonstrating its importance in tumorigenesis." (PMID 33226370, 2020). "In mouse studies conducted by the Cerwenka group, only IL-2-primed NK cells and tumor-infiltrating NK cells were observed to express CTLA-4." (PMID 33384695, 2020). "The upregulation of CTLA-4 expression is one of the mechanisms adopted by tumor cells to evade anti-tumor immune response." (PMID 33519815, 2020).
tumor (continued). "Surprisingly, pH-sensitive anti-CTLA-4 antibodies are more effective in intratumour Tregs depletion and rejection of large established tumours by avoiding CTLA-4 downregulation and due to their increased bioavailability." (PMID 32680511, 2020). "Compared to GB/PC-KO, GB/PC-WT mice displayed increased IL-2 levels, tumor proliferation, FoxP3+PD-1+CTLA-4+ TILs, higher Tgfβ, and Il10 mRNA expression levels, and a CD4+/CD8+ ratio of 4:1." (PMID 33335860, 2020). "Synergistic effects were observed in preclinical studies where tumour-bearing mice were treated with the combination of imatinib and anti-CTLA-4 antibody." (PMID 33207697, 2020). "We further identified expression of CTLA-4 and FoxP3 in both interstitial and tumor cells, with a positive association between interstitial expression of CTLA-4 and FoxP3, which was also associated with lower serum CTLA-4 levels." (PMID 32123292, 2020). "Blocking inhibitory immune checkpoint interactions between T-cells and tumour cells responsible for tolerance, i.e., blocking immune suppressor signals such as CTLA-4 and PD-1, has been a powerful strategy for cancer immunotherapy." (PMID 32937961, 2020). "Immunotherapy, especially against CTLA-4 and PD-1/PD-L1 signaling to promote anti-tumor immunity, shows promising progression-free survival and recovery in many patients." (PMID 32714859, 2020). "Addition of anti‐CTLA‐4 antibodies to ILP‐TNF/Mel/SM led to a significant increase of T helper cells and also caused a reduction of intra‐tumoural CD3+CD4+Foxp3+ regulatory T cells." (PMID 32419365, 2020). "This suggests that once established, antitumor immunity generated by our ISV + α-CTLA-4 regimen can effectively kill tumor cells in the brain." (PMID 32690669, 2020). "Immunotherapies targeting immune checkpoint molecules, including PD1, CTLA-4, and Tim-3 have been a major breakthrough in cancer therapy and have changed our understanding of host-tumor interactions." (PMID 32632113, 2020). "In mouse models lacking CD4+ T lymphocytes (CD4–/–) or CD8 T lymphocytes (CD8–/–) through genetic knockout, it was found that blockade of CTLA-4 and PD-1 facilitated tumor vessel normalization by the activation of CD4+ Th1 cells." (PMID 32983126, 2020). "As expected, anti–CTLA-4 significantly reduced the tumor growth, while promoting tumor necrosis as revealed by dark pigmented cells (dead tumor cells had increased expression of melanin and appeared as darkly pigmented cells) and TUNEL assay." (PMID 32817121, 2020). "At the same time, metformin can also enhance the antitumor effect of PD1/CTLA‐4 blockade by reducing tumor hypoxia." (PMID 34766109, 2020). "This favors tumor escape from T-cell immunity, thereby conferring resistance to anti–CTLA-4 therapy." (PMID 32850400, 2020). "By interfering with T cell activation, CTLA-4 hampers antitumor-related immune responses and promotes tumor growth." (PMID 33335608, 2020). "Gao and colleagues observed in different murine tumor models higher expression of CTLA-4 in intermediate ILC1s (intILC1s, being CD49a+CD49b+EOMES+), that are impaired in their ability to secrete IFN-γ but not TNF-α." (PMID 33255582, 2020). "In particular, we show here for the first time that they activate different pathways downstream CTLA-4 in tumor and NK cells, shedding light also on unrevealed potential roles of this receptor on different cell populations." (PMID 32781690, 2020). "CCL14 expression in HCC negatively correlated with expression of several immune cell markers, including exhausted T cell markers, PD-1, TIM-3 and CTLA-4, suggesting its role in regulating tumor immunity." (PMID 31927532, 2020). "Wnt1-driven tumors achieved complete tumor regression when DCR-BCAT treatment was combined with CTLA-4 or PD-1 antibodies." (PMID 32408880, 2020). "B. fragilis activates Th1 cells to cross-react with bacterial antigens and new tumor antigens, enhancing the efficacy of anti-CTLA-4." (PMID 32522267, 2020).
tumor (continued). "Working on the inhibitory receptor/ligand combinations between T-cells and tumor cells, such as the programmed cell death protein-1 (PD-1) and programmed cell death-ligand 1 (PD-L1), and the cytotoxic T lymphocyte antigen-4 (CTLA-4/B7)." (PMID 32617246, 2020). "When combined with an anti-CTLA-4 immune checkpoint inhibitor, regulatory T cells in the tumor microenvironment also decreased compared to controls." (PMID 33260534, 2020). "In a mice model, anti-CTLA4 MoAbs or IL-2 led in T-cells and TNF-a accumulation and Ezh2 expression, which caused immunogenicity loss of tumor, lower antigen expression and resistance to immunotherapy." (PMID 32344837, 2020). "Tumor heterogeneity has been described for key modulators of the ICB response such as PD-L1, and the neoantigens and tumor clonality has already been reported as a predictor of enhanced response to anti-CTLA4 and anti-PD-1 treatment in NSCLC." (PMID 31968651, 2020). "Altogether these results confirm that CTLA-4 is indeed expressed on tumor cells and on NK cells and it plays a critical role in NK cell anti-tumor activity." (PMID 32024070, 2020). "Ipilimumab is a monoclonal antibody binding to CTLA-4, which can enhance T cells activation and promote tumor immunity." (PMID 33469538, 2020). "Tumors take advantage of immune checkpoint pathways to shut down T cell activity and inhibit the anti-tumor immune response, mediated by proteins such as PD-L1 and CTLA-4." (PMID 33182232, 2020). "Collectively, these results demonstrate that in this luminal-like BC, RL inhibition improves the anti-tumor response to anti-CTLA4 (in the early setting) and anti-PD-L1 (for established tumors) through inhibition of RANK signaling in the tumor cells." (PMID 33303745, 2020). "On the other hand, a combination of Anti-CD96 with doxorubicin chemotherapy, anti-CTLA-4, or anti-PD-1 has shown more efficacy in inhibiting experimental metastases in three different tumor models." (PMID 32117298, 2020). "That is to say, the depletion of tumor-infiltrating Tregs was closely related to CTLA-4-related toxicities and CTLA-4 molecule inactivation." (PMID 33123120, 2020). "MC38 and MCA101OVA tumor models were less responsive to anti-CTLA-4 with no CR observed, in these two models adding butyrate abolished the anti-tumor effect of anti-CTLA-4." (PMID 32358520, 2020). "Among the various mechanisms involved in the immunological escape of tumor cells, activated immune checkpoint pathways, including the PD-1/PD-L1 and CTLA-4 axis, are the central suppressors amenable to therapeutic inhibition (left)." (PMID 33102516, 2020). "PTT mediated with these iron-oxide nanoparticles in combination with anti-CTLA-4 induced a significant inhibition in the tumor growth and, even more important, provided a memory effect that protected the mice against tumor re-challenge." (PMID 32225049, 2020). "Tumor cell autophagy increases the expression of inhibitory molecules, such as PD-1 and CTLA-4, which block antitumor cytotoxic responses." (PMID 33335860, 2020). "Recent publications show increased expression of the immune inhibitory ligand and receptors (PD-L1/CTLA4) on tumor cells and/or tumor-infiltrating immune cells." (PMID 32029828, 2020). "An important development in cancer immunotherapy is a re-evaluation of the mechanism by which anti-CTLA-4 antibodies induce tumor rejection." (PMID 31991588, 2020). "In the tumor microenvironment, activation of both proteins protects tumor cells while CTLA-4 regulates the immune response early when the T-cells are activated, and PD-1 acts later on to induce T-cell apoptosis and eventually stop the immune response." (PMID 32665852, 2020). "We observed similar results using the MC38 tumor model in Aire+/+ and Aire−/− mice treated with anti-CTLA4 or isotype antibodies." (PMID 32641748, 2020). "Functionally, circulating and tumour-infiltrating PD-1+ eTregs were highly activated, showing higher expression of CTLA-4 than shown by PD-1− eTregs." (PMID 32680511, 2020).
tumor (continued). "The three antibodies inhibited the growth of both CTLA-4-positive tumor cells also independently from the immune system." (PMID 32781690, 2020). "The results showed that high tumor-specific MHC-I expression in response to anti-CTLA-4 therapy was essential, but anti-PD-1 or immune combination therapy was not effective." (PMID 32974156, 2020). "CTLA-4 is overexpressed on regulatory T lymphocytes (Tregs) and activated CD4+ and CD8+ T cells, whereas, anti-CTLA-4 antibodies enhance anti-tumor immunity." (PMID 33375686, 2020). "The selective depletion of tumor-infiltrating Tregs enhanced by preserving CTLA-4 recycling led to the cancer therapeutic effect of anti-CTLA-4 antibodies." (PMID 33123120, 2020). "Although the complete mechanism of the anti-tumor effects of ipilimumab are still under debate, it is clear that gut microbiota influence the CTLA-4 blockade because GF mice fail to respond to this ICB." (PMID 32944086, 2020). "Other than PD-1 and CTLA-4, many immune checkpoints exist on the surface of T cells, and the interactions between them and ligands on tumor cells are potentially important to determine the clinical response of ICIs." (PMID 35582437, 2020). "Complete tumor elimination has been observed in up to 90% mice treated with antagonist of A2A receptor accompanied by anti-PDL1 or anti-CTLA4 antibody." (PMID 32793604, 2020). "The combination of anti-CTLA4 and radiation therapy is curative, but only where the host has good pre-existing immunity to the tumor." (PMID 32866185, 2020). "The immunoregulatory molecules cytotoxic T-lymphocyte antigen 4 (CTLA-4), programmed death receptor 1 (PD-1), and programmed death ligand 1 (PD-L1) were also higher in high IL-33 tumor samples than in low IL-33 tumor samples." (PMID 33634017, 2020). "In a tumor setting, CTLA-4 expression by T cells can restrain an otherwise effective anti-tumor response." (PMID 32614928, 2020). "Further, inhibition of Kit has been demonstrated to enhance the antitumor activity of immune checkpoint inhibitors (anti–CTLA-4 and anti–PD-1) by selectively reducing the immunosuppressive M-MDSCs population in Colon26 mouse tumor model." (PMID 32849585, 2020). "Immune and stromal scores for tumor tissues were calculated using ESTIMATE; we then assessed the associations between these scores and PD-1 and CTLA4 expression." (PMID 33072070, 2020). "Despite this, the anti-tumor efficacy of anti-CTLA-4 was reduced in mice supplemented with sodium butyrate." (PMID 32358520, 2020). "In this study, we demonstrate that microbial systemic SCFA (butyrate and propionate) influence anti-CTLA-4 anti-tumor effect in mice models and in patients with MM and treated with ipilimumab." (PMID 32358520, 2020). "We showed that such a PDT-based vaccine outperforms the anti-CTLA4 antibody administration, leading to significant tumor growth delay and tumor-free survival." (PMID 32120810, 2020). "Strikingly, these novel pH-sensitive anti-CTLA-4 mAbs prevent irAEs with an enhanced preclinical anti-tumor efficacy." (PMID 32787882, 2020). "Monoclonal antibody (mAb) based therapies targeting cytotoxic T-lymphocyte antigen 4 (CTLA-4), programmed cell death 1 (PD-1) or programmed cell death ligand 1 (PD-L1) have improved patient survival across various tumor types 1-8." (PMID 32042331, 2020). "Checkpoint blockade therapy, for example using antibodies against CTLA-4 and PD-1/PD-L1, relieves T cells from the suppression by inhibitory checkpoints in the tumor microenvironment; thereby achieving good outcomes in the treatment of different cancer types." (PMID 32714324, 2020). "In tumors treated with radiotherapy in combination with anti-CTLA-4 therapy, a significantly increased tumor-to-heart ratio was observed." (PMID 32086762, 2020). "For instance, one recent study showed that the anti-tumor efficiency of CD47/SIRPα blockades can be reinforced upon combination with CTLA-4, PD-L1 or other ICI blockers." (PMID 32824974, 2020).
tumor (continued). "UCNP/ICG/RB-mal combined with anti-CTLA-4 synergistically enhanced the antitumor immune response, regulated the tumor immunosuppressive microenvironment, and effectively prevented tumor metastasis." (PMID 33240857, 2020). "Immune checkpoint blockade (ICB) targeting PD-1 and CTLA-4 is now implemented into the standard therapies of an increasing number of tumor entities, resulting in durable responses and increased survival in a substantial number of patients." (PMID 32071302, 2020). "High expression of PD-L2 and CTLA-4 and low expression of PD-1 in the tumor microenvironment of PMBCL suggest efficacy of immune checkpoint blockade for SCT-ineligible patients or patients with refractory disease." (PMID 32366834, 2020). "Combining ADT with TI-Tregs depletion using a depleting anti-CTLA-4 antibody significantly delayed the development of castration resistance and prolonged the survival of a fraction of tumour-bearing mice." (PMID 32680511, 2020). "Survey of clinicaltrials.gov shows that while some trials evaluating the combinations with anti-CTLA-4 have failed or halted, there are many ongoing trials aiming to evaluate safety and efficacy against various tumor types." (PMID 32679922, 2020). "Our results above demonstrated that there are heterogeneous responses to anti-PD-1 and anti-CTLA-4 not only at the bulk tumor level but also at the clonal level." (PMID 33059736, 2020). "The 200 mm3 (at start) group start treated with the anti-CTLA-4 antibody (10mg/kg, biw, ip) on day seven produced anti-tumor activity with a statistical difference (**P < 0.01) (the tumor volumes were 394±34 mm3 vs. 2,106±205 mm3)." (PMID 32805718, 2020). "Compared with traditional anti‐CTLA4 therapy, recently developed tumour‐conditional anti‐CTLA4 therapy depleted tumour‐infiltrated Tregs, while preserving tissue‐resident Tregs, which preserved antitumour effects and reduced multiorgan immune toxicity." (PMID 32881301, 2020). "Here we describe an experimental approach for intravital imaging of adoptive T-cell morphology, mobility and trafficking in a skin-flap tumor model, following immune modulation with immune checkpoint inhibitors (ICIs) targeting PD-L1 and CTLA-4." (PMID 32793206, 2020). "We postulate that low CCL14 expression in the tumor microenvironment diminishes the Ca2+ influx and upregulates the expression of inhibitory immune checkpoint proteins, PD-1, CTLA-4 and TIM-3 on the exhausted T cells." (PMID 31927532, 2020). "CTLA-4 is mainly expressed on Tregs, which decrease T cell immune responses and help tumor cells realize immune escape." (PMID 32158356, 2020). "Combinatorial PD-1 and CTLA-4 blockade increased the frequency and function of tumor-specific CD8 T cells." (PMID 33177175, 2020). "The anti-CTLA-4 aDVD exhibits a potent anti-cancer effect by increasing tumor-infiltrating CD8+ T cells and decreasing the tumor-infiltrating Treg population in allogenic tumor-bearing mice and further preventing treatment-induced multiorgan toxicity." (PMID 32586313, 2020). "In one study, a soluble PD-1-based TWIST1 DNA vaccine in conjunction with anti-CTLA-4 antibody significantly reduced tumor growth and lung metastasis, presumably by increasing IFN-γ+ TNFα+ CD8+ T-cells." (PMID 32937885, 2020). "Little information is currently available for on-treatment tumor biomarkers for anti-CTLA-4 therapy." (PMID 32793228, 2020). "In contrast, the proportion of CD8+ T cells was increased in TIL cultures when anti-CTLA-4 antibody was added to the tumor fragments during the initial TIL growth compared to TIL outgrowth when cultured only with IL-2." (PMID 32127601, 2020). "Several pre-clinical studies have shown that PD-1 and/or CTLA-4 blockade can improve tumor control in combination with tumor cell vaccines." (PMID 32508825, 2020). "The combination of lower dose RX-5902 (35 mg/kg) plus anti-CTLA-4 resulted in greater tumor growth inhibition compared to RX-5902 (35 mg/kg) alone (p = 0.007)." (PMID 33148223, 2020).